FLI1 (Fli-1 proto-oncogene, ETS transcription factor)
Diseases named in the same sentence as FLI1 in open-access papers (continued):
Sharing a sentence is not in itself a finding about the gene and the disease.
tumor (377 papers, 1994 to 2026). "Higher FLI1 protein expression was associated with increased histological grades and enriched stromal features, suggesting a role in tumor aggressiveness and microenvironment modulation." (PMID 41300765, 2025). "Transfection experiments with other, structurally related EWSR1 chimeras, like EWSR1::FLI1, support this concept, although the detailed underlying mechanism, including the list of chimera-dysregulated tumor-driver genes, is still to be elucidated." (PMID 39769457, 2024). "Aligning with findings from MC38 mouse models, tumor intrinsic FLI1 deficiency significantly attenuated tumor growth, intratumoral Kyn production, and the frequency of both exhausted CD8+ T cells and Tregs within the TME." (PMID 38816360, 2024). "Our results revealed that the depletion of these T cell populations significantly mitigated the tumor-suppressive effects observed with FLI1 deficiency." (PMID 38816360, 2024). "Collectively, our findings illuminate tumor-intrinsic FLI1 deficiency as a critical determinant in augmenting CD8+ T cell-mediated tumor clearance." (PMID 38816360, 2024). "Strikingly, FLI1 deficiency within tumor cells culminated in decreased PD-1 and TIM-3 expression on CD8+ T cell surfaces, concomitant with increased IFN-γ and TNF-α release by CD8+ T cells." (PMID 38816360, 2024). "Due to formation of the EWSR1/FLI1 fusion gene in the tumor genome, the cell loses one wild type EWSR1 allele." (PMID 36875767, 2023). "Here, tissue circ-FLI1 was associated with tumor size, TNM stage, distant metastasis, and unfavorable overall survival." (PMID 35647294, 2022). "These in vivo data displayed that interfering circ-FLI1 caused tumor growth inhibition of CC by regulating miR-197-3p and DKC1." (PMID 35647294, 2022). "We then assessed potential associations of FLI1 expression with tumor and clinical parameters, including tumor differentiation, stage, and survival." (PMID 31231464, 2019). "The high expression of Fli-1 was significantly associated with advanced tumor stage, positive lymph nodal involvement, and poor OS and DFS (p< 0.05)." (PMID 24923303, 2014). "When we sequenced the PEST domain of Fli-1 tumours, only four out of eight primary samples had mutations." (PMID 23667468, 2013). "In contrast, we found increased NOTCH1 expression in all Fli-1 T cells and detected Notch1 mutations in all tumours." (PMID 23667468, 2013). "Interestingly, FLI1 expression in breast cancer samples was positively associated with both immune and stromal infiltration, underscoring FLI1’s role in tumor stroma and immune infiltration." (PMID 41300765, 2025). "Beyond its diagnostic utility, EWSR1::FLI1 may also establish targetable molecular dependencies, offering promising avenues for therapeutic innovation in this otherwise genomically sparse tumor." (PMID 41514642, 2025). "Low-methylation-induced or ncRNA-mediated downregulation of FLI1 is associated with poor prognosis, and FLI1 might regulate the tumor immune microenvironment via a cell-type-specific target genes manner in BRCA." (PMID 38448802, 2024). "Our results show that FLI-1 down-expression was associated with tumor stage and patient OS." (PMID 37047006, 2023). "It was shown that FLI1 was associated with the progression of tumour, served as a prognostic marker in many types of tumour and also acted as a potential therapeutic target in tumours." (PMID 32249526, 2020). "Altered expression of FLI1 is also linked with tumor aggressiveness and poor prognosis." (PMID 30867568, 2019). "Given that inflammation is a well-known pro-tumor factor, ECs that have undergone EndMT mediated by ERG/FLI1 loss may promote tumor progression in an inflammation-dependent manner." (PMID 30500808, 2018). "Increasing expression of Fli-1 is associated with tumor development and may possibly with malignancy." (PMID 28418872, 2017). "Increasing expression of Fli-1 is one of the common scenarios during tumor development and may be associated with the disease malignancy." (PMID 24923303, 2014).
tumor (continued). "This is an attractive possibility because MSC may not only be uniquely susceptible to EWS/FLI1 action but also be a source of CD133+ tumor stem cells and high aldehyde dehydrogenase levels." (PMID 21052545, 2011). "Furthermore, to confirm whether our protein profiles were significantly associated with EWS/FLI1 onco-protein and tumor malignancy, we performed cell proliferation assays based on either NPM1 or EWS/FLI1 siRNA knockdown." (PMID 29581854, 2018). "Here, we report that tissue-specific expression of EWSR1::FLI1 in zebrafish induces tumor formation that recapitulates the histologic and molecular hallmarks of human ES, including small round blue cell morphology and characteristic biomarker expression." (PMID 41977317, 2026). "A study showed that EWS/FlI1 represses miR-22 expression, and its restoration leads to significant inhibition of tumor cell proliferation, clonogenic growth, and anchorage-independent survival." (PMID 40429954, 2025). "Mechanistically, LSD1 has been shown to co-occupy genomic loci with ETS family transcription factors, including FLI1, suggesting direct regulatory interplay in transcriptional programs relevant to tumor progression." (PMID 41300765, 2025). "miR-22 has been identified as a tumor suppressor miRNA in ES that functions in opposition to the oncogenic program driven by the EWS/FlI1 fusion oncoprotein." (PMID 40429954, 2025). "Immunohistochemical staining for CD31, CD34, and FLI-1 supports the diagnosis of a borderline-malignant tumor." (PMID 40428263, 2025). "FLI1-high tumors also exhibited elevated stromal and immune scores, indicating a role in remodeling the tumor microenvironment." (PMID 41300765, 2025). "Future studies leveraging multi-omics will be essential to disentangle the tumor-intrinsic and microenvironmental contributions of FLI1 expression." (PMID 41300765, 2025). "In our case the tumour cells reacted positively with CD31, vimentin, and FLI-1, which supports the endothelial origin of the tumour." (PMID 40542819, 2025). "Using breast cancer mouse models, LSD1 inhibition influenced FLI1 target genes related to tumor progression." (PMID 41300765, 2025). "Our study reveals a therapeutically targetable mechanism that promotes EWSR1::FLI1 expression and ES tumor growth." (PMID 39894896, 2025). "The transcription factors PBX1 and FLI1, known regulators involved in angiogenesis, were observed to be upregulated in TC-ECs from tumour tissue, further emphasising their roles in endothelial differentiation and vascular remodelling." (PMID 40427675, 2025). "The study addresses the following research objectives: (a) the expression pattern of FLI1 in IBC, (b) the association of FLI1 expression with histopathological grading and prognosis in IBC, and (c) the influence of FLI1 on the tumor microenvironment in IBC." (PMID 41300765, 2025). "Given the central role of FLI1 in cellular regulation, understanding its expression patterns in breast cancer and its contributions to tumor progression and metastasis is critical." (PMID 41300765, 2025). "Inhibition of C1GALT1 using a genetic or pharmacological inhibitor, such as ITZ, reduces SMO O-glycosylation, Hh signaling, and EWSR1::FLI1 expression, resulting in decreased ES cell viability and tumor growth in mice." (PMID 39894896, 2025). "Since EWS::FLI1 depends on these acetyltransferases to sustain enhancer activity and regulate tumor-promoting genes, inhibiting their enzymatic functions leads to EWS::FLI1 destabilization and enhanced therapeutic sensitivity." (PMID 41228232, 2025). "We found evident activation of FLI1-targeted genes in myeloid cells of tumor samples compared with those of normal tissues." (PMID 38448802, 2024). "Blocking of ACSL6 impairs the tumor growth and upregulates FLI1, which reduces the levels of COLs and compromises irradiation‐induced autophagy, leading to considerable therapeutic benefits during radiotherapy." (PMID 39206814, 2024).
tumor (continued). "Most FLI-1-targeted drugs mainly target FLI-1 in tumour cells or fibroblasts, with little attention given to FLI-1 in ECs." (PMID 39107790, 2024). "The ETS oncogene FLI1 is a major driver of tumor initiation and progression of diverse types of malignancies." (PMID 38461240, 2024). "We next ascertained the role of tumor-intrinsic FLI1 in CD8+ T cell exhaustion by coculturing activated CD8+ T cells with either FLI1-knockout (KO) or wild-type (WT) NPC cells." (PMID 38816360, 2024). "Concerning the regulatory role of FLI1 in immune cell activity in the BRCA microenvironment, we found that FLI1 was significantly downregulated in BRCA tissues analyzed using bulk RNA-seq data derived from tumor tissues containing various cells." (PMID 38448802, 2024). "We discovered several cell-communication-related target genes of FLI1 in immune cells, including myeloid cells and T cells, that showed differential expression between tumor and normal tissues." (PMID 38448802, 2024). "This occurs mainly because FLI-1 regulates the expression of critical factors involved in various pathological processes, such as tumour cell growth, proliferation, differentiation, apoptosis, genomic instability, and immunity." (PMID 39107790, 2024). "The examination indicated positive Vimentin findings in the cytoplasm and positive FLI-1 in the nuclei of the tumour cells." (PMID 38735214, 2024). "In the context of our study, we identify FLI1 as a pivotal transcription factor that regulates IFN-γ-induced kynurenine (Kyn) synthesis through a CBP/STAT1-IDO1 axis in tumor cells." (PMID 38816360, 2024). "Numerous studies have shown that the level of FLI-1 in tumour cells is closely related to patient prognosis." (PMID 39107790, 2024). "Based on these findings, the selectively targeting of tumor FLI1 activity emerges as a promising adjuvant strategy in cancer immunotherapy." (PMID 38816360, 2024). "A total of 468 genes targeted by FLI1 were primarily activated in myeloid cells and endothelial cells in normal tissues but only in myeloid cells in tumor tissues." (PMID 38448802, 2024). "In contrast to UBASH3B, knockdown of FLI1 in erythroleukemia cells upregulates UBASH3A expression, raising the possibility of a tumor suppressor function for this variant." (PMID 38461240, 2024). "The impact of FLI-1 on ECs within the tumour microenvironment is primarily demonstrated through its involvement in tumour metastasis, including angiogenesis and endothelium-mesenchymal transition (EndMT) processes." (PMID 39107790, 2024). "In vivo analysis, employing the implantation of FLI1 WT and FLI1-KO MC38 cells into C57BL/6 mice, further verified that FLI1-KO tumors manifested conspicuous growth attenuation, as manifested by reduced growth rate and terminal tumor weight." (PMID 38816360, 2024). "Then, we applied scRNA-seq data of BRCA to investigate the role of FLI1 on the tumor microenvironment via integrating a series of single-cell analyses." (PMID 38448802, 2024). "The expression of FLI1 in the tumor tissues (from 23 patients) and samples from the low immunity score group (12 patients) was much greater than that in the adjacent skin tissue (from 23 patients) and the samples of the high immunity score group (11 patients)." (PMID 38280909, 2024). "Contrarily, our findings underscore the critical role of tumor-intrinsic FLI1 in promoting T cell exhaustion." (PMID 38816360, 2024). "We thank B.D. Crompton and K. Stegmaier for sharing their RNA-Seq EwS tumor data sets, B. Schäfer for the EWS:FLI1 expressing plasmid, A.M. El-Naggar for mouse xenograft and K. Specht and K. Steiger for EwS tumor sections." (PMID 38530366, 2024). "More importantly, we identify that tumor-intrinsic FLI1 mediates the overproduction of Kyn in response to IFN-γ via CBP/STAT1-IDO1 axis, leading to CD8+ T cell exhaustion and Treg differentiation." (PMID 38816360, 2024).
tumor (continued). "More importantly, combination of FLI1 KO or YK-4-279 with anti-PD1 therapy delivered a more pronounced tumor suppression." (PMID 38816360, 2024). "The variability of EWS::FLI1 expression and transcriptional activity among individual tumor cells is emerging as a critical determinant of epigenetic heterogeneity, tumor cell phenotype, and disease progression." (PMID 39524141, 2024). "In this study, we identify tumor-intrinsic FLI1 as a critical mediator in impairing T cell anti-tumor immunity." (PMID 38816360, 2024). "Endothelial cells and myeloid cells in tumor tissues exhibit high FLI1 expression and high transcription activity of FLI1-targeted genes." (PMID 38448802, 2024). "The abnormal expression of FLI-1 in malignant tumour cells and excessive vascular growth in the local tumour microenvironment can promote tumour occurrence and metastasis." (PMID 39107790, 2024). "Recently, it has been proposed that fusion protein levels can fluctuate in individual tumor cells, generating specific genetic profiles that are associated with EWSR1::FLI1 high and low levels and that in turn are associated with different cell behaviors." (PMID 37511533, 2023). "MS0621 reprograms the EWSR1::FLI1-regulated alternative splicing pattern, decreasing tumor-characteristic intron retention and altering the inclusion of exons harboring highly conserved sequences." (PMID 36793594, 2023). "First, we established a zebrafish xenograft metastasis model by transplanting DiI dye-labeled Caki-1 and 786-O cells expressing shKSRP or shCtrl in transgenic Tg(fli1: EGFP) zebrafish embryos which led to extensive dissemination of tumor cells." (PMID 37580757, 2023). "The critical dependence on EWSR1::FLI1 and its exclusive expression in tumor cells makes it an attractive candidate for drug development." (PMID 36793594, 2023). "Compared with the VECTOR group, the FLI1 group exhibited increased NPC tumor growth in terms of size, volume, and weight in response to radiation." (PMID 36814284, 2023). "Intriguingly, low expression of this EWSR1::FLI1 target gene impaired EwS vessel morphology and increased tumor hypoxia." (PMID 36915100, 2023). "FLI-1 high-expression obtained prominent immune cell tumor infiltration compared to patients with FLI-1 low-expression." (PMID 37047006, 2023). "Considering the important role of angiogenetics in the process of tumor growth, the effects of chlorahololide D on intersegmental vessel formation in transgenic zebrafish Tg(fli1: EGFP) were estimated." (PMID 37894550, 2023). "In summary, evidence exists that HIF-1-a, like EWSR1::FLI1, contributes to tumor heterogeneity in EwS." (PMID 36915100, 2023). "The expression of ERG and FLI1 was decreased in ECs within tumors, suggesting that EndoMT is induced in the tumor microenvironment (see the “Roles of EndoMT in Tumor EC” section)." (PMID 35130955, 2022). "Here, we review what is currently understood about EWS::FLI1 activity, the cell autonomous and tumor microenvironmental factors that regulate it, and the downstream consequences of these activity states on tumor progression." (PMID 36505823, 2022). "Next, we used Zebrafish (Danio rerio) [Tg(fli1:EGFP)] tumor xenograft model to further validate our findings." (PMID 36182968, 2022). "FLI1 acts as a tumor promoter, although, interestingly, reduced expression of FLI1 has been shown to induce epithelial-mesenchymal transition in human umbilical vein endothelial cells." (PMID 36099287, 2022). "It is thus likely that intrinsic differences in the chromatin state, DNA methylation profile, and transcription factor repertoire of the cell of origin influence EWS::FLI1 activity, cell state, and tumor behavior." (PMID 36505823, 2022). "Here, we will review the current state of knowledge in the field regarding EWS::FLI1 fusion activity and the tumor cell intrinsic and extrinsic factors that regulate it." (PMID 36505823, 2022).
tumor (continued). "RT-qPCR data showed a high level of circ-FLI1 in CC tumor tissues than the normal tissues; its expression was overall upregulated in CC cell lines versus normal cell lines." (PMID 35647294, 2022). "These EWS::FLI1-upregulated TFs greatly expand the number of gene targets that are deregulated by EWS::FLI1 and in some cases they are also required for efficient tumor outgrowth." (PMID 36505823, 2022). "It was found that the expression of FLI1 in tumor tissue (23 cases) and the lower immunity score group (12 cases) were dramatically higher than that in adjacent skin tissue (23 cases) and the higher immunity score group (11 cases), respectively." (PMID 33971970, 2021). "The patient-derived ES cancer cell lines used to establish tumor foci in the ovarian tissue all contained an EWS-FLI1 translocation, including the most common functional gene fusion of EWS exon 7 with FLI1 exon 6 (type I) in cell line EW8." (PMID 34640378, 2021). "Herein, the red fluorescence-labeled tumor cells were injected into the Tg(fli1:eGFP) transgenic zebrafish line showing GFP expression in vasculature." (PMID 34831440, 2021). "In order to further validate the expression of FLI1 in TAMs, we analysis the transcriptome data of TAMs extracted from different groups of tumor tissues before and after chemotherapy." (PMID 33971970, 2021). "The impact of nitric oxide (NO) in tumor progression was confirmed in 2 dpf Tg(fli1:EGFP) embryos injected in the yolk sac with rat GBM-labeled cells (GV1A1)." (PMID 33802571, 2021). "A TAM-tumor cell co-culture experiment proved that FLI1 was involved in tumor cell invasion, and FLI1 also showed a unique pattern in patients." (PMID 33971970, 2021). "The excised tumor tissue was labeled with anti‐FLI1 antibody to confirm that the probe was molecularly targeted to E/F and thus labeled the tumor tissue." (PMID 34392592, 2021). "To analyze tumor-induced angiogenesis, we generated xenografts in Tg(fli1:eGFP) zebrafish hosts, which have the vasculature labelled with enhanced Green Fluorescent Protein (eGFP)." (PMID 32630796, 2020). "We found that the FLI1 expression levels of the normal samples were significantly increased when compared with those of their paired tumour samples, which was consistent with previous work." (PMID 32249526, 2020). "Another case is friend leukemia virus integration 1 (FLI1), a transcription factor that promotes tumor growth." (PMID 32194627, 2020). "Compared with the low expression FLI1 subtype, patients in the high expression FLI1 subtype had stronger immune cell infiltration and anti‐tumour immune activities." (PMID 32249526, 2020). "Although fucoidan did not affect the normal zebrafish in vivo, it highly decreased tumor formation and angiogenesis in the xenograft and fli1 Tg models, respectively." (PMID 31936539, 2020). "Except for the tumour purity, the average values of the high expression FLI1 subtype were significantly higher than those in the low expression FLI1 subtype for of all the other features." (PMID 32249526, 2020). "We also downloaded the transcriptional profiles of 113 paired normal samples for BRCA and compared the FLI1 expression levels of the normal samples with their paired tumour samples." (PMID 32249526, 2020). "Under s-μg, the tumor marker EWS/FLI1 is intensified, while targeting CXCR4, which influences adhesion proteins, did not affect spheroid formation." (PMID 31810195, 2019). "While FLI1 has a known role in hematopoiesis, these studies lend evidence towards a tumor suppressor role for FLI1 in various epithelial tumors, especially in the gastrointestinal tract." (PMID 31231464, 2019). "As important findings, tumor marker EWS/FLI1 was more intensely expressed on the gene and protein level, and CXCR4, although highly upregulated under s-μg, does not seem to affect spheroid formation, as we showed by its inhibition." (PMID 31810195, 2019).